OLFML3 (olfactomedin like 3)
Diseases named in the same sentence as OLFML3 in open-access papers (continued):
Sharing a sentence is not in itself a finding about the gene and the disease.
Sepsis (1 paper, 2025). Sepsis is defined as life-threatening organ dysfunction caused by a dysregulated host response to infection. "It was found that Olfml3 knockout significantly reduced the survival of mice during LPS-induced sepsis." (PMID 40083707, 2025).
uterus cancers (1 paper, 2021). "To address this, we first examined the expression of the OLFML3 protein in colorectal, kidney, lung, esophagus, prostate, and uterus carcinoma tissue sections and the corresponding healthy tissues using immunohistochemistry (IHC) or immunofluorescence (IF) staining." (PMID 34572851, 2021).
tumor (30 papers, 2009 to 2026). "Antibody-mediated blockade of OLFML3 and deletion of host Olfml3 decreased the recruitment of tumor-promoting tumor-associated macrophages and increased infiltration of the tumor microenvironment by NKT cells." (PMID 34572851, 2021). "Our study identified OLFML3 as a key regulator of angiogenesis, lymphangiogenesis, pericyte coverage, tumor-associated macrophage recruitment, and enhanced NKT lymphocyte recruitment associated with its antitumor effects." (PMID 34572851, 2021). "However, OLFML3 has been implicated in both EC-mediated neoangiogenesis and pericyte-mediated tumor revascularization." (PMID 36498941, 2022). "In conclusion, our findings demonstrate the therapeutic benefits of antibody-mediated targeting of OLFML3 and provide important insight into the underlying mechanisms, which involve the inhibition of tumor angiogenesis, lymphangiogenesis, pericyte coverage, and immune cell infiltration." (PMID 34572851, 2021). "Next, we investigated whether blocking the expression of OLFML3 correlates with the recruitment of tumor-associated macrophages (TAMs) and NKT cells to human CRC." (PMID 34572851, 2021). "We conclude that tumor-associated endothelial cells and pericytes express Olfml3." (PMID 34572851, 2021). "OLFML3 showed high expression in macrophages/monocytes and lower levels in malignant cells, further underscoring its role in the tumor microenvironment." (PMID 40104502, 2025). "Within the context of cancer, increased OLFML3 immunostaining has been documented in the tumor-infiltrating vasculature of colorectal, uterine, lung and prostate carcinoma." (PMID 36498941, 2022). "Among these genes, RT-qPCR and western blotting analysis verified that OLFML3, which plays a role in tumor-related angiogenesis, was decreased in the ROBO1WT group, while it was recovered in the ROBO1E280* group." (PMID 35615148, 2022). "The central circadian clock gene plays a crucial role in regulating tumor immunity by upregulating OLFML3 transcription in glioblastoma, which recruits immunosuppressive microglia into the tumor microenvironment." (PMID 35326729, 2022). "Next, we evaluated OLFML3 expression in CRC patient-derived tumor xenografts (PDX) (21 primary tumors and 6 metastases of admitted tumor patients before the start of therapy, and transplanted into CB17-SCID mice (immunodeficient mice))." (PMID 34572851, 2021). "The combination of anti-OLFML3 and anti-PD-1 antibodies increases tumor infiltration by inflammatory myeloid cells, B cells, T lymphocytes, and NKT cells, and inhibits tumor growth more effectively than either agent used alone." (PMID 34572851, 2021). "Deletion of Olfml3 led to a significant decrease in MC38 tumor growth and volume relative to those in WT animals." (PMID 34572851, 2021). "Treatment of multiple in vivo tumor models with OLFML3-blocking antibodies and deletion of the Olfml3 gene from mice decreased lymphangiogenesis, pericyte coverage, and tumor growth." (PMID 34572851, 2021). "Taken together, our observations suggest that inhibiting OLFML3 stimulates antitumor immunity, possibly via effects on tumor blood and lymphatic vessels, and inflammatory cells." (PMID 34572851, 2021). "To explore the role of host Olfml3 during tumor growth and vascularization, we subcutaneously inoculated wild-type (WT) and Olfml3 knockout mice with MC38 CRC cells." (PMID 34572851, 2021). "We previously identified Olfml3 as a novel proangiogenic factor that promotes tumor growth in the LLC1 mouse lung tumor model." (PMID 34572851, 2021). "We used recombinant monoclonal antibodies specific for OLFML3 to block tumor angiogenesis, lymphangiogenesis, and pericyte coverage in mouse models and monitored the effects on tumor growth." (PMID 34572851, 2021). "Both of the rec-anti-OLFML3 antibodies decreased MC38 tumor growth significantly relative to control antibody treatment." (PMID 34572851, 2021).
tumor (continued). "The new anti-OLFML3 antibodies developed for therapeutic purposes inhibit tumor growth, tumor angiogenesis, lymphangiogenesis, pericyte coverage, and the expression of lymphangiogenic factors." (PMID 34572851, 2021). "To characterize OLFML3 expression in human cancer and its role during tumor development, we undertook tissue expression studies, gene expression analyses of patient tumor samples, in vivo studies in mouse cancer models, and in vitro coculture experiments." (PMID 34572851, 2021). "Blockade of Olfml3 activity with specific antibodies has been shown to inhibit tumour vascularization, pericyte coverage and tumour growth in a mouse xenograft cancer model." (PMID 27916653, 2017). "More recently, treatment with anti-OLFML3 (olfactomedin-like 3) was reported to be significantly effective in reducing tumor vascularization, pericyte coverage on tumor vessels, and tumor growth." (PMID 26000022, 2015). "Spatial mapping by barcode RNA-FISH linked these transcriptional states to their tissue context and showed that OLFML3 expression partially co-localized with a dominant subpopulation at the tumor-liver interface, marking the invasive fronts of metastatic growth." (PMID 42039662, 2026). "Subsequently, we knocked down OLFML3 in ROBO1E280* cells and examined whether the knockdown of OLFML3 could restore the lost tumor-suppressing effects of ROBO1E280*." (PMID 35615148, 2022). "OLFML3, a member of the olfactomedin domain-containing secreted glycoprotein family, was reported to be involved in neovascular formation during embryonic development and tumor progression." (PMID 35615148, 2022). "Notably, the expression of OLFML3 correlates with the expression of immune checkpoint inhibitors, including the PD-L1/PD-1 mRNA, in human tumor samples." (PMID 34572851, 2021). "To test whether the reduced number of TAMs was responsible for the reduced tumor angiogenesis after therapy with rec9F8 or in Olfml3 knockout mice, we experimentally depleted macrophages by treating tumor-bearing mice with clodronate liposomes." (PMID 34572851, 2021). "Therefore, we also monitored the effect of tumor treatment with anti-OLFML3 antibodies on the expression of human and mouse angiogenesis-associated transcripts in human DLD1 CRC tumors treated with rec9F8, or bevacizumab." (PMID 34572851, 2021). "We extensively described that several important tumor-growth-promoting cell types are affected by anti-OLFML3 antibody treatment (blood and lymphatic endothelial cells, pericytes, and TAMs) that are altogether linked during tumor development, blood vessel formation, and immune cell infiltration." (PMID 34572851, 2021). "Moreover Olfml3 is expressed by endothelial cells and pericytes within the tumor stroma, where it promotes vascularization and growth of mouse Lewis lung carcinoma (LLC1)." (PMID 34572851, 2021). "Targeting Olfml3 has been shown to suppress tumor growth and angiogenesis." (PMID 35087569, 2021). "In this study, we used bioinformatics analysis of human datasets, immunostaining and mRNA expression analyses of tumor samples, human PDX models, and human/mouse tumor graft models to demonstrate that OLFML3 is overexpressed in multiple carcinomas relative to the corresponding healthy tissues." (PMID 34572851, 2021). "However, even though OLFML3 is a candidate target for tumor targeting, little is known about its relevance to human cancer or its therapeutic potential." (PMID 34572851, 2021). "OLFML3 may constitute a target for antiangiogenic therapy as further in vivo experiments demonstrated that anti-Olfml3 antibodies impaired tumor growth and angiogenesis." (PMID 31083655, 2019). "Inhibition of Olfml3 in tumours has shown to affect both ECs and pericytes." (PMID 27916653, 2017). "Similarly, our study suggests that Olfml3 may restrict microglial immune responses, thereby contributing to the markedly immunosuppressed tumor microenvironment of GBM." (PMID 34884869, 2021).
tumor (continued). "In CRC patients, OLFML3 mRNA expression positively correlated with shorter RFS, the angiogenic CMS4 subtype, and transcripts encoding proangiogenic and lymphangiogenic factors, and negatively with antiangiogenic molecules, suggesting a role for OLFML3 in tumor angiogenesis and lymphangiogenesis." (PMID 34572851, 2021). "Strikingly, anti-OLFML3 mAb treatment decreased the plasma levels of mouse Plgf in human DLD1 and mouse MC38 tumor models, whereas DC101 treatment had the opposite effect." (PMID 34572851, 2021). "Both mouse Olfml3 and human OLFML3 interact with BMP4, a proangiogenic factor involved in tumor cell migration and invasion." (PMID 34572851, 2021). "We showed extracellular matrix modifications of the tumor and upregulation of factors generally secreted by CAFs such as CXCL12, ASPN and OLFML3." (PMID 26437222, 2015). "GSC reliance on BMAL1/CLOCK complex was found to be in part stimulated by downstream transcriptional upregulation of olfactomedin like 3 (OLFML3), a novel chemokine that functions to promote immune-suppressive microglia infiltration into the tumor microenvironment." (PMID 36635730, 2023). "In addition, it enhances the transcriptional expression of OLFML3, a recently discovered chemokine that recruits immunosuppressive microglia to the TME to trigger pro-tumor immunity." (PMID 37700840, 2023). "Looking ahead, it is possible that anti-OLFML3 therapy, administered concurrently with anti-VEGF therapy, may work synergistically in the GBM microenvironment to mitigate neoangiogenesis and tumor growth." (PMID 36498941, 2022). "Furthermore, OLFML3 is a potential target gene of ROBO1, and its inhibition restores the lost tumor-suppressing effects of ROBO1E280*." (PMID 35615148, 2022). "Bevacizumab treatment of DLD1-xenograft-bearing mice reduced the expression of mouse Olfml3 (host-derived) and human OLFML3 (tumor-derived, although not significantly) mRNA in tumor samples." (PMID 34572851, 2021). "Although the mechanism of OLFML3-mediated NK-like T cell recruitment is not yet clear and is outside of the scope of this study, NK cells promote tumor cell apoptosis and secrete the immune-stimulatory cytokine IFN-γ." (PMID 34572851, 2021). "In our models, anti-OLFML3 antibodies promoted tumor homing of NK-like T cells but did not increase the recruitment of T lymphocytes." (PMID 34572851, 2021). "Olfml3 is also a immediate target gene for all TGF-β isoforms in mouse microglia and is a crucial factor in TGF-β-induced pro-tumor phenotypic transformation of microglia, and also promotes tumor progression by increasing tumor cell invasion and migration capacity." (PMID 37700840, 2023). "Many cytokines secreted by tumor cells can recruit macrophages to the TME, but some of them are exclusively produced by CSCs: CCL2, CCL3, CCL5, CXC motif chemokine ligand 12 (CXCL12), olfactomedin-like 3 (OLFML3), stromal-cell-derived factor-1b (Sdf1b), IL-6, IL-33, and CSF-1." (PMID 35740975, 2022). "To confirm that recombinant anti-OLFML3 antibodies did not induce tumor cell death via ADCC or complement, we generated a glycosylation-deficient rec46A9 variant (rec46A9M) bearing a mutation in the Fc region at site N297 (N297Q) that prevents mAb recognition of Fc receptors by complement effectors." (PMID 34572851, 2021). "Interestingly, we observed that one of the eight mice treated with anti-PD-1 antibody did not develop a primary tumor, while, remarkably, three of the eight mice did not develop a primary tumor with the combination of anti-PD-1 and anti-OLFML3." (PMID 34572851, 2021). "However, combined treatment with the two antibodies had no additive effect on MC38 tumor growth, suggesting that OLFML3 may act along the CSF1/CSF1-R axis." (PMID 34572851, 2021).
cancer (9 papers, 2009 to 2025). A tumor composed of atypical neoplastic, often pleomorphic cells that invade other tissues. "OLFML3 has been implicated in the promotion of angiogenesis in several cancers." (PMID 36498941, 2022). "Importantly, targeting OLFML3 has been linked with improved outcomes in preclinical cancer models." (PMID 36498941, 2022). "In our study, M2 macrophages were characterized by the presence of anti-inflammatory markers Gas6, Ch25h, and Olfml3, as well as the pro-cancer marker Hpgds." (PMID 41361104, 2025). "Therefore, it is possible that there are multiple mechanisms leading to microglial-mediated OLFML3-induced angiogenesis in health and cancer." (PMID 36498941, 2022). "OLFML3 was expressed at high levels, mainly in blood vessels, in multiple human cancers." (PMID 34572851, 2021). "The role of the proangiogenic factor olfactomedin-like 3 (OLFML3) in cancer is unclear." (PMID 34572851, 2021). "OLFML3 is a disease biomarker in colon cancer and has been shown to promote neoangiogenesis, epithelial-to-mesenchymal transition, and metastasis in several cancers." (PMID 34884869, 2021). "Importantly, OLFML3 has broad relevance to cancer progression." (PMID 34884869, 2021). "However, the relevance of OLFML3 to human cancer is unreported." (PMID 34572851, 2021). "Olfactomedin-like 3 (OLFML3), a secreted glycoprotein, is an established proangiogenic factor in many cancers, but its role in GBM neoangiogenesis is unknown." (PMID 36498941, 2022). "Interestingly, OLFML3, ENTPD1, and members of the EMILIN family are reported to be involved in regulating angiogenesis in other cancers, which is in line with the unique enrichment of angiogenic processes in the CAF-elevated N-glycoproteome observed in our study." (PMID 36671461, 2022).
infection (3 papers, 2021 to 2025). The state of being infected such as from the introduction of a foreign agent such as serum, vaccine, antigenic substance or organism. "Next we sought to examine the effects of RAB5C or OLFML3 knockout on the infection of clinical RV strain." (PMID 34686207, 2021). "The fact the OLFML3 affected RV-activated SOCS3 expression at late time point (24 h after infection) suggested an indirect or delayed interaction between OLFML3 and SOCS3." (PMID 34686207, 2021). "The top-scoring output—OLFML3 (ranked by VarElect as one of the highest-phenotype-relevance genes for hsa-miR-155-5p)—was independently supported by literature showing its role in IFN-I suppression during RV14 infection." (PMID 40981223, 2025). "Furthermore, it will be interesting to investigate whether OLFML3 functions as an antagonist of IFN signaling during the infection of other enteroviruses." (PMID 34686207, 2021). "Notably, OLFML3 was found to be an RV-inducible dependency factor that promoted the infection." (PMID 34686207, 2021). "Meanwhile, compared to Olfml3+/+ mice, Olfml3-/- mice had increased death rate and elevated inflammatory phenotype in response to LPS stimulation or PAO1 infection." (PMID 40083707, 2025).
bacterial infection (2 papers, 2024 to 2025). "Some overexpressed genes in BM samples are associated with infections, such as ASRGL1, NR2F6, and OLFML3 for bacterial infection." (PMID 38902725, 2024). "Unlike previous reports, the current study investigated a more general role of OLFML3 in macrophages during bacterial infection." (PMID 40083707, 2025). "In the present study, we sought to explore the in vivo and in vitro function of OLFML3 during lipopolysaccharide (LPS) stimulation or bacterial infection." (PMID 40083707, 2025).
OLFML3 also shares sentences with these, for which no sentence is quoted: neurodegenerative disease (2 papers); amyloid (1); amyotrophic lateral sclerosis (1); asthma (1); Cognitive impairment (1); depression (1); Down syndrome (1); esophageal cancer (1); frontotemporal dementia (1); Goniodysgenesis (1); meningioma (1).